RNU6-936P (RNA, U6 small nuclear 936, pseudogene)
Gene: Small nuclear RNA gene on chromosome 2 (24,676,309 to 24,676,415, forward strand). Ensembl gene ENSG00000206732.
Homologues: Orthologues: chimpanzee U6 (99% identical), dog U6 (93% identical), macaque U6 (92% identical), dog U6 (86% identical), dog U6 (78% identical). Paralogues in human: RNU6-21P (92% identical), RNU6-144P (89% identical), RNU6-15P (89% identical), RNU6-211P (89% identical), RNU6-1103P (88% identical), RNU6-1179P (88% identical), RNU6-128P (88% identical), RNU6-16P (88% identical), RNU6-310P (88% identical), RNU6-31P (88% identical), RNU6-333P (88% identical), RNU6-463P (88% identical), and 1289 more.